MEMO1 (mediator of cell motility 1)
Diseases named in the same sentence as MEMO1 in open-access papers (continued):
Sharing a sentence is not in itself a finding about the gene and the disease.
cancer (continued). "Further, siRNA mediated reduction of MEMO1 in a variety of cancer cell lines was shown to reduce their migratory potential, relative to controls, in response to HRG stimulation." (PMID 33172038, 2020). "Knockdown of Circ-MEMO1, prior to injecting cancer cells into nude mice, resulted in smaller tumors with increased miR-101-3P levels and decreased KRAS levels, relative to control targeted cells." (PMID 33172038, 2020). "Using previously published genome-wide screens, we analyzed gene essentiality scores derived from 1028 cancer cell lines displaying a wide range of MEMO1 expression levels." (PMID 38640016, 2024). "MEMO1 overexpression may help to maintain normal metabolism of cancer cells by increasing iron levels in mitochondrial under hypoxic conditions." (PMID 38640016, 2024). "MEMO1 overexpression may help to maintain normal metabolism of cancer cells by increasing iron levels in mitochondrial under hypoxic conditions that are frequently found in tumors." (PMID 38640016, 2024). "We conclude that MEMO1 is an iron-binding protein that modulates iron homeostasis in cancer cells." (PMID 38640016, 2024). "Still, the remarkable structural similarity between MEMO1 and dioxygenases strongly suggests that MEMO1 may catalyze redox reactions involved in biosynthesis or breakdown of a signaling molecule in cancer cells." (PMID 38640016, 2024). "Following this lead, we asked if enrichment of these gene sets in the MEMO1 network of the GOF-GIs may reflect specifically high sensitivity of high-MEMO1 cancer cells to the disruptions of iron metabolism." (PMID 38640016, 2024). "Eleven genes were found to be more essential in cancer cell lines with high expression of MEMO1 (GOF-GIs), six genes were more essential in the cell lines with low-MEMO1 levels (LOF-GIs), and one (FTH1) showed inconsistent types of interactions between different databases." (PMID 38640016, 2024). "Since cancer cells have increased Cu levels, and free Cu ions may promote ROS formation, unless controlled, Memo1 may act as a Cu(I) chaperone in cancer cells." (PMID 36067318, 2022). "This Memo1 functionality may be a safety mechanism to cope with the increased demand of Cu ions in cancer cells." (PMID 36067318, 2022). "Intriguingly, Trpm7 which is transcriptionally increased in the two Memo1 KO mouse models presented here, is needed for EGF-induced cancer cell migration, a function apparently opposite to Memo1’s role in cancer cell motility, where MEMO1 expression is upregulated." (PMID 32706793, 2020). "The somatic mutation frequency of the MEMO1 locus is relatively low (intOgen), suggesting that it is not a cancer driver gene in the typical sense." (PMID 33172038, 2020). "How might the expression of MEMO1 be upregulated in the context of cancer?" (PMID 33172038, 2020). "Our previous genome-wide analysis of MEMO1 genetic interactions across multiple cancer cell lines revealed that gene sets involved in mitochondrial respiration and the TCA cycle are enriched among the gain-of-function interaction partners of MEMO1." (PMID 40278406, 2025). "Several candidates identified in our experiment, either in CuCl2-or CuCl2 and LA-treated groups, are directly involved in cancerogenesis (such as MEMO1, ATOX1, L1CAM, RABGGTA, MAP2K7 and others, and may be of potential interest for anti-cancer research." (PMID 39290994, 2024). "Moreover, the copper-dependent enzyme lipoxygenase (LOX) catalyzes the cross-linking of collagen and elastin in the extracellular matrix (ECM) and interacts with the Mediator of Cell Motility 1 (MEMO1), which is involved in cancer cell migration." (PMID 36986466, 2023). "Thus, increased Circ-MEMO1 ultimately results in higher levels of KRAS, promoting cancer cell proliferation and survival." (PMID 33172038, 2020). "The increased expression of Trpm7 induced by EGF or by the absence of Memo1 with opposite role on cancer cell migration will require more in-depth studies." (PMID 32706793, 2020).
cancer (continued). "Structural similarity of MEMO1 to the iron-containing dioxygenases and a clear link between MEMO1 homolog MHO1 and iron metabolism that emerged from genome-wide analyses of GIs networks in yeast led us to a hypothesis that MEMO1 plays a role in iron metabolism in cancer cells." (PMID 38640016, 2024).
kidney disease (1 paper, 2023). "To assess a potential role of Memo1 in kidney disease‐driven Fgf23 expression, we therefore challenged mice of both genotypes with AKI induced by intraperitoneal injection of 240 mg/kg of body weight folic acid." (PMID 36967231, 2023).
MEMO1 also shares sentences with these, for which no sentence is quoted: androgenous alopecia (1 paper); cervical cancer (1); colon cancer (1); Failure to thrive (1); frontotemporal dementia (1); Global developmental delay (1); hyperphosphatemia (1); hypogonadism (1); Infertility (1); Intellectual disability (1); intestinal disease (1); lymph node metastasis (1); renal failure (1); squamous cell tumors (1).